APOE (apolipoprotein E)
Diseases named in the same sentence as APOE in open-access papers (continued):
Sharing a sentence is not in itself a finding about the gene and the disease.
cognitive decline (continued). "The apolipoprotein E epsilon 4 (ApoE ɛ4) allele is considered to be a risk factor for AD, and ApoE ɛ4 may influence the rate of cognitive decline in early AD." (PMID 32587611, 2020). "We tested their predictive value individually, simultaneously, and—because the presence of the APOE e4 allele has previously been found to predict cognitive decline in this same cohort during almost the same period of life —in models also including the APOE e4 status of the participants." (PMID 30760887, 2020). "Therefore, even in a different cohort and measuring a different outcome, APOE ε4 and diabetes were reliably associated with cognitive decline in late life." (PMID 32767997, 2020). "ApoE-ε4 carriers are at higher risk for cognitive decline than their non-ε4 counterparts." (PMID 32645032, 2020). "In addition to increased risk for LOAD, female carriers of APOE ε4 exhibit more severe presentation of endophenotypes including more severe Aβ and tau pathology, worse cognitive decline and worse atrophy." (PMID 32859588, 2020). "Age, APOE*4, and diabetes were associated with faster cognitive decline." (PMID 31335910, 2019). "Similar to studies in 1259 middle-aged and older men from Eastern Finland, the identified associations of cholesterol and cognitive decline were conserved after further adjusting for APOE ε4 among a middle-aged and elderly Chinese, possibly due to prominent distribution of APOE ε3." (PMID 31888696, 2019). "APOE*4 carriage and diabetes were also both independently associated with cognitive decline." (PMID 31335910, 2019). "Physical fitness may influence individual susceptibility in the ApoE-4 allele and increased risk of cognitive decline with advancing age." (PMID 31591322, 2019). "Whether the increased DNA methylation of the APOE CpG-165, CpG-190 and CpG-198 is a cause or a consequence of cognitive decline remains to be studied." (PMID 30897703, 2019). "Additionally, the relationship between the ApoE-4 allele and cognitive declines showed a gene–dose effect in elderly men and women, with homozygotes showing more risk of developing impaired cognitive function than heterozygotes." (PMID 31591322, 2019). "In addition to those risk factors, evidence indicates that the genetic component “APOE ε4” interacts with sex to affect the risk of cognitive decline." (PMID 31921740, 2019). "Indeed, research has shown that a low level of physical activity is associated with a higher risk of cognitive decline, particularly among APOE ε4 carriers." (PMID 31798373, 2019). "The APOE E4 allele, depression and neuroticism have each been found to have adverse associations with contemporaneously measured cognitive ability and subsequent cognitive decline." (PMID 29451880, 2018). "In addition, several studies have demonstrated that the impairment of glymphatic pathway activity caused by sleep deprivation triggered APOE-related neuronal dysfunction in AD, leading to cognitive decline." (PMID 30429819, 2018). "If it is confirmed that increased total stage N3 time among APOE ε4/ε4 carriers reflects an overactive downscaling of synapses during sleep, these results might in part explain the high risk of AD and age-related cognitive decline among APOE ε4/ε4 carriers." (PMID 29370207, 2018). "A 2010 systematic review highlighted smoking and the apolipoprotein E (APOE) ε4 genotype as risk factors for greater cognitive decline, whereas better physical health was identified as a protective factor (Plassman, Williams, Burke, Holsinger, & Benjamin, 2010)." (PMID 29745686, 2018). "We assessed whether APOE was a risk factor for cognitive decline among older Taiwanese adults using nationally representative data." (PMID 30339707, 2018). "Finally, recent studies have paid more attention to individuals at high risk for AD, such as amnestic mild cognitive impairments and ApoE-4 allele carriers as well as subjective cognitive decline." (PMID 29763448, 2018).
cognitive decline (continued). "Likewise, future studies shall take into account the modulatory role of the APOE‐ε4 allelic load, which has been previously associated to deficient hippocampal pruning and significant cognitive decline assessed longitudinally." (PMID 29972619, 2018). "In this study, we examined whether APOE genotype was associated with age-related cognitive decline among cognitively healthy older Taiwanese adults." (PMID 30339707, 2018). "Moreover, prior work demonstrating an interaction of Aβ and ApoE ε4 genotype in healthy older adults reported lower cognitive performance and faster rates of cognitive decline only in subjects with both risk factors." (PMID 29527500, 2018). "This pathological CSF signature is a key feature in AD diagnosis, and the CSF profile, potentially combined with neuroimaging data, has the ability to predict cognitive decline and conversion to AD independently of established risk factors such as age, sex and apolipoprotein E (ApoE) genotype." (PMID 28441967, 2017). "Thus, our data point to the existence of independent pathophysiological pathways mediating cognitive decline in AD patients according to the APOE polymorphism." (PMID 29062035, 2017). "Interestingly, a recent study investigated the effect of interaction of APOE ε4 allele status with BMI on cognitive decline and showed that cognitive decline was differentially associated with BMI and APOE ε4 allele status." (PMID 28915562, 2017). "Furthermore, previous studies have indicated that a positive effect of physical activity on age-related changes of the brain, such as hippocampal atrophy and amyloid burden, as well as on cognitive decline, is strongest in carriers of the APOE ε4 allele." (PMID 27757080, 2016). "Based on the association between the ε2 allele and increased use of hippocampus-dependent spatial strategies, the study suggests an important potential mechanism by which the APOE ε2 allele is associated with decreased cognitive decline and risk of developing AD." (PMID 27468260, 2016). "APOE ε4 also influences the clinical course of AD, causing earlier onset of dementia, higher degrees of brain atrophy, lower temporal, hippocampal, amygdala volumes and significant thinner cortices, and faster cognitive decline." (PMID 27410431, 2016). "Further study to identify modifiers that protect Chinese from cognitive decline despite APOE ε4-conferred loss in brain volume could provide a unique opportunity to identify factors that promote cognitive resilience against AD." (PMID 25738563, 2015). "The ε4 allele of the APOE gene is a potent risk factor for cognitive decline over time." (PMID 26102276, 2015). "Additionally, those who are cognitively healthy APOE-ε4 carriers have exhibited structural damage and associated cognitive decline compared with non-E4 carriers as observed by magnetic resonance imaging (MRI)." (PMID 25859282, 2015). "However, the lessened risk for cognitive decline experienced by physically active individuals with the APOE 4 gene, offers strength to the notion of causality, in regard to specificity of susceptibility." (PMID 24885250, 2014). "Because the purpose of this endophenotype-based approach is to identify variants implicated in disease, we tested whether the PSEN1, p.E318G is associated with AD risk, tau/Aβ pathology or rate of cognitive decline in an APOE dependent manner." (PMID 23990795, 2013). "Additionally, we found that in the presence of at least one APOE-ε4 allele, p.E318G is associated with more Aβ plaques and faster cognitive decline." (PMID 23990795, 2013). "However, among APOE-ε4 allele carriers, those who were physically active less than one hour per day had an odds ratio for cognitive decline that was nearly 4 times greater than APOE-ε4 allele carriers who reported more than one hour per day of PA." (PMID 24961307, 2013).
cognitive decline (continued). "Findings of increased functional connectivity between medial temporal lobe (MTL) regions and other regions known to be affected by AD (e.g. posterior cingulate) in young E4 carriers also suggest that ApoE begins to be expressed in AD-associated brain regions long before cognitive decline." (PMID 23152815, 2012). "Because of apoE's essential genetic, and therefore presumably biochemical, contribution to AD pathology and cognitive decline, it is critical that its role in the AD pathogenic pathway/amyloid cascade be elucidated in order for therapeutics based on apoE to be designed." (PMID 22844635, 2012). "All experiments carried out so far in vitro or in transgenic mice indicate that the ability of Aβ to form neurotoxic filaments or oligomers and cause cognitive decline are increased in the presence of apoE, particularly mouse apoE and human apoE4, with apoE2 being protective." (PMID 22844635, 2012). "In addition, apolipoprotein E (ApoE) is strongly associated with AD in terms of cognitive decline and disease onset: ApoE, especially the ε4 allele, has been observed promoting an inflammatory reaction." (PMID 19895675, 2009). "The strong correlations between APOE2 alleles and many lipid species suggest that lipids in the blood may mediate the genetic effect of APOE on cognitive function, where individuals with certain lipid profile can present “reduced/increased” risk of cognitive decline." (PMID 41042284, 2025). "In cancer, the association between APOE and hormone effects has not been extensively investigated, yet studies have shown that APOE ε2 may be protective against cognitive decline following chemotherapy for breast cancer in older patients, whilst APOE ε4 carriers may be at greater risk." (PMID 40149482, 2025). "Similarly, post-hoc analyses of two large-scale trials (FINGER and MAPT) have shown that individuals at increased risk of future cognitive decline—such as APOE-ε4 carriers or those with positive amyloid PET scans—tend to derive greater cognitive benefits from MLI compared to non-carriers." (PMID 40664536, 2025). "In conclusion, the APOE ε4 allele might play a pivotal role in modulating brain dynamic functional activities in AD, which may contribute to the association between Aβ pathology and cognitive decline." (PMID 40642909, 2025). "Additionally, the presence of biomarkers (e.g., APOE ε4) may help identify patients at risk of progressive cognitive decline." (PMID 41408330, 2025). "In addition, it has been shown that females carrying the APOE ε4 allele may experience more pronounced cognitive decline compared to males with the same genotype." (PMID 39886338, 2024). "Hence, it can be hypothesized that during the prodromal phase of AD, psychotic features might be more strongly related to incident cognitive decline among those carrying at least one APOE e4 allele." (PMID 38473892, 2024). "Finally, we did not adjust for other possible variables, such as blood glucose, lipid profiles, and APOE ɛ4 allele carrier status, which could influence the risk of cognitive decline." (PMID 37031269, 2023). "Additionally, the APOE ε2 allele has been associated with decreased cognitive decline during aging." (PMID 36468416, 2023). "Thus, we suggest that individuals with LBD, particularly females with one or more APOE ε4 alleles, could be considered candidates for treatment with amyloidocentric drugs, should they show efficacy in slowing cognitive decline in patients with AD." (PMID 37652560, 2023). "However, it is well known that cognitive decline is a complex multifactorial process and could be affected either directly or indirectly by age, sex, the apolipoprotein E ε4 allele (ApoE-ε4), education and the clinical characteristics of type 2 diabetes." (PMID 35173604, 2022).
cognitive decline (continued). "The apolipoprotein E (APOE) epsilon 4 (ε4) allele is well established as the strongest genetic risk factor for cognitive impairments and hypertension, and therefore, may moderate the association between hypertension and cognitive decline." (PMID 35624902, 2022). "In addition, the apolipoprotein (APOE) ε4 gene is a risk factor for Alzheimer’s disease and may lead to greater sensitivity to AC-mediated cognitive decline." (PMID 36506252, 2022). "Interestingly, APOE was strongly associated with cognitive decline in both CHAP samples." (PMID 35807939, 2022). "ApoE ε4 allele(s) status has also been associated with disease progression from MCI to AD, such that the onset of AD could be reported 8–16 years earlier among individuals with the ApoE ε4 allele(s), compared to non-ApoE ε4 allele carriers, indicating as well even faster rates of cognitive decline." (PMID 36062144, 2022). "Consequently, the higher age at baseline might have increased the power to detect the interaction of OCRS with APOE-ε4 in our study and reduced the likelihood of detecting the association with cognitive decline in the whole cohort." (PMID 36571008, 2022). "There are many factors that contribute to the rate of cognitive decline, such as age of disease onset, gender, education, extrapyramidal signs, behavioral disorders, vascular risk factors and the most known AD susceptibility genetic locus, apolipoprotein E (APOE) genotypes." (PMID 34214049, 2021). "Moreover, the rate of cognitive decline was associated with the APOE ε4 allele and SORL1 rs3737529." (PMID 34214049, 2021). "Additionally, Koch and colleagues have shown that only in APOE ε4 AD patients there is a strong association between cognitive decline, impaired cortical plasticity and CSF t-tau values, suggesting a relative susceptibility to APOE ε4 patients to the amount of tau-related pathological burden." (PMID 34408639, 2021). "Our result that the APOE ε2 allele may confer protection against cognitive decline for cancer survivors selected to receive chemotherapy adds a new dimension to the body of evidence supporting a role of APOE genotype broadly and strengthens evidence suggesting parallels between CRCD and AD." (PMID 33748669, 2021). "Substantial evidence suggests that the ApoE ɛ4 allele is related to increased Aβ deposition, rapid thinning of the cortex, and accelerated cognitive decline, while the ApoE ɛ2 allele is related to a decrease in Aβ deposits, slower thinning of the cortex, and slower cognitive decline." (PMID 32587611, 2020). "Thus, we tested whether the GxE interaction between APOE genotype and PA was associated with cognitive decline in the general population of older individuals, using data from three prospective population-based cohort studies with longitudinal measurements." (PMID 32110803, 2020). "Using outcomes identified as sensitive to AD progression, we estimated possessing an APOE ε4 allele accounted for approximately 8% of variance in scores, and modest sample sizes would be sufficient to detect a significant treatment effect to delay cognitive decline in an RCT." (PMID 30503169, 2019). "However, the extent to which APOE genotype modulates associations of dietary cholesterol/egg intakes and serum cholesterol levels with cognitive decline remains relatively unknown." (PMID 31888696, 2019). "Regardless, the possibility of APOE-ε4 being associated with a process of cognitive decline that begins subtly in midlife may warrant the search for potential therapeutic window to these deleterious effects, or the instigation of a screening process for potential AD, earlier in the life course." (PMID 29317609, 2018). "Hence, these findings suggest that the link between cognitive decline and vascular pathology is present and that APOE genotype may contribute to this association." (PMID 25333200, 2014).
cognitive decline (continued). "Indeed, co-morbid conditions aggravating the outcome after ischemia entail a peripheral inflammatory response including plasma IL-6 upregulation, and high plasma IL-6 levels have been associated with worsened cognitive decline in older people and in APOE*4 carriers." (PMID 23957944, 2013). "The APOE ε4 allele might also be associated with domain-specific cognitive decline in normal aging." (PMID 21215387, 2011). "First, the cross-sectional design limits our ability to infer the temporal progression of APOE ε4-related connectivity changes or their relationship to future cognitive decline." (PMID 40585225, 2025). "In contrast, APOE ε4-negative participants experienced a significant cognitive decline while on insulin." (PMID 41146261, 2025). "The synergistic interaction between elevated FSH levels and APOE ε4 carrier status exacerbate cognitive decline." (PMID 41180813, 2025). "Some studies have reported a positive effect of APOE ε2 on reducing cognitive decline in both healthy and demented populations, as well as improved performance in short-term and long-term memory and executive function and attention." (PMID 41226628, 2025). "Astrocytes predominantly synthesize the APOE gene product within the central nervous system and have been recognized as the determinant contributing to the accelerated age-related cognitive decline in individuals." (PMID 40177376, 2025). "Interestingly, expected cognitive decline caused by APOE ε4 may be moderated by advanced education." (PMID 39940989, 2025). "For example, the impact of lifestyle factors such as alcohol and coffee consumption, as well as metabolites like omega-6 fatty acids, can be evaluated across different APOE genotypes to assess their roles in cognitive decline." (PMID 40725187, 2025). "We emphasize the importance of carefully examining the sex-specific effects of APOE ε2 on cognitive decline and brain metabolism, structure, and function throughout the lifespan." (PMID 41226628, 2025). "Although the role of APOE in aging and cognition has been extensively studied, the mechanisms by which the APOE2 allele protects against cognitive decline and promotes longevity remain elusive." (PMID 41042284, 2025). "AD patients carrying the APOC1 risk allele have been reported to experience faster cognitive decline and an earlier conversion from MCI to AD when they also carry the APOE ε4." (PMID 40369256, 2025). "For example, CETP and APOE facilitate cholesterol metabolism, and function in shared pathways of late‐onset AD and cognitive decline during aging." (PMID 40665476, 2025). "The present investigation seeks to elucidate the interactive mechanisms by which sleep duration and APOE genotype jointly modulate early stage cognitive decline and AD pathogenesis." (PMID 40994826, 2025). "Given previous evidence of the efficacy of MLI (5,9,10,), we conducted a proof-of-concept trial to investigate the efficacy of combining EGCG with an intensive MLI for 12 months to prevent cognitive decline in APOE-ɛ4 carriers with SCD." (PMID 40664536, 2025). "APOE ε4 allele: Research indicates that carriers of the APOE ε4 allele who engage in long-term recreational use of psychotropic drugs, especially MDMA and cannabis, are at a higher risk of accelerated cognitive decline and memory impairment." (PMID 39377784, 2025). "Apolipoprotein E (APOE) allele 4 (APOE4), one of the robust genetic risk factors for AD, has also been associated with cognitive decline in terms of memory, executive function, language, and global cognitive function." (PMID 40725187, 2025). "One notable finding from this study was that the APOE ε4-positive participant exhibited the most pronounced mitochondrial impairment, cognitive decline, and amyloid burden." (PMID 40002463, 2025). "Recent evidence shows that elevated baseline CSF PDGFRβ is associated with increased hippocampal Ktrans and predicts future cognitive decline in APOE ε4 carriers." (PMID 40145342, 2025).